FLOT1 (flotillin 1)
Diseases named in the same sentence as FLOT1 in open-access papers (continued):
Sharing a sentence is not in itself a finding about the gene and the disease.
hepatocellular carcinoma (10 papers, 2013 to 2025). A malignant tumor that arises from hepatocytes. "Some studies showed that FLOT1 was negatively associated with cancer survival, including hepatocellular carcinoma, tongue squamous cell cancer, and non‐small cell lung cancer." (PMID 40066501, 2025). "The upregulated expression of Flotillin-1 was associated with tumor cell progression and poor prognosis in hepatocellular carcinoma." (PMID 35990908, 2022). "In hepatocellular carcinoma, FLOT1 overexpression enhances insulin signaling, which promotes proliferation and metastasis." (PMID 40335491, 2025). "MiR-214-3p inhibited cell proliferation and metastasis in hepatocellular carcinoma by downregulating Flotillin-1." (PMID 35990908, 2022). "The present study was aimed to investigate the clinical and prognostic significance of FLOT1 in hepatocellular carcinoma (HCC)." (PMID 23840303, 2013). "Correlations between FLOT1 expression and clinicopathologic characteristics of hepatocellular carcinoma patients." (PMID 23840303, 2013). "The YTHDF1/EIF3C axis is involved in the invasion process in ovarian cancer; EIF3H participates in the invasion of hepatocellular carcinoma and the EIF4A3/FLOT1 pathway promotes invasion and tumor proliferation in lung adenocarcinoma." (PMID 40705973, 2025). "In vitro and in vivo studies on hepatoma cells revealed that luteolin treatment promotes apoptosis and tumor suppression through up-regulation of miR-6809-5p which down-regulates Flotillin 1 by directly binding to the 3′UTR of Flotillin-1 gene mRNA." (PMID 34295245, 2021). "We addressed caveolin-1 and flotillin-1 expression in 90 human hepatocellular carcinoma (HCC) and adjacent noncancerous tissues (ANT) samples by SDS-PAGE and immunoblotting with specific antibodies." (PMID 25243186, 2014).
gastric cancer (9 papers, 2015 to 2025). A primary or metastatic malignant neoplasm involving the stomach. "In gastric cancer, FLOT1 expression is associated with poor disease-free survival." (PMID 40335491, 2025). "Additionally, the phosphorylation of BCAR1 at Tyr 410 is specifically associated with FLOT1 induced gastric cancer invasion and migration." (PMID 37928269, 2023). "In gastric cancer, FLOT1 is involved in tumor progression and metastasis by regulating EMT signaling." (PMID 40335491, 2025). "Previous studies have shown that FLOT1 promotes gastric cancer progression and metastasis by interacting with BCAR1, specifically regulating its phosphorylation and translocation." (PMID 40303305, 2025). "Based on these results, it appears that phosphorylation of BCAR1 Tyr410 site is very important in FLOT1 induced gastric cancer cell migration and invasion." (PMID 37928269, 2023). "With the results above, we concluded that FLOT1 promotes gastric cancer cell proliferation, migration and invasion." (PMID 37928269, 2023). "With the knowledge that FLOT1 was involved in several types of cancer and overexpressed in gastric cancer, we further investigated the function of FLOT1 in gastric cancer cells." (PMID 37928269, 2023). "In this work, we find overexpression of FLOT1 promotes proliferation, migration and invasion of gastric cancer cells and tumor growth, while knockdown of FLOT1 inhibits gastric cancer proliferation, migration and invasion in vitro and in vivo." (PMID 37928269, 2023). "All these results from rescue experiments suggested that BCAR1 mediate FLOT1 induced gastric cancer proliferation, migration and invasion through ERK signaling." (PMID 37928269, 2023). "To further investigate the molecular mechanism of FLOT1 in gastric cancer, we transfected plasmids expressing HA-FLOT1 into AGS cells." (PMID 37928269, 2023). "In this study, we find FLOT1 promotes gastric cancer cell proliferation, migration and invasion through FLOT1/BCAR1/ERK pathway." (PMID 37928269, 2023). "Overexpression of FLOT1 increases, while knockdown of FLOT1 decreases gastric cancer cell proliferation, migration and invasion." (PMID 37928269, 2023). "Here, we find FLOT1 promotes gastric cancer cell progression and metastasis by interacting with BCAR1, through ERK signaling." (PMID 37928269, 2023). "To identify the effect of Flotillin-1 expression level on the clinical prognosis of gastric cancer, we analyzed the data from The Cancer Genome Atlas (TCGA)." (PMID 35990908, 2022). "The migration and invasion ability of gastric cancer cells was upregulated by overexpressing Flotillin-1." (PMID 35990908, 2022). "In this study, we identified that overexpression of Flotillin-1 decreased the epithelial marker E-cadherin and upregulated mesenchymal markers such as N-cadherin, Vimentin and Snail in gastric cancer cells." (PMID 35990908, 2022). "To examine the role of Flotillin-1 in gastric cancer metastasis, we performed Transwell and wound healing assays to detect the abilities of migration and invasion." (PMID 35990908, 2022). "To identify the function of Flotillin-1 in gastric cancer, we overexpressed Flotillin-1 in two gastric cancer cell lines SGC-7901 and AGS." (PMID 35990908, 2022). "Flotillin-1 promotes gastric cancer metastasis through inducing EMT, and promotes EMT of gastric cancer via stabilizing Snail." (PMID 35990908, 2022). "E-cadherin was upregulated, and N-cadherin, Vimentin and Snail were decreased in Flotillin-1-knockdown gastric cancer cells." (PMID 35990908, 2022). "In summary, our study demonstrate Flotillin-1 can participate in the development of gastric cancer, and promotes gastric cancer metastasis." (PMID 35990908, 2022). "The ubiquitination level of Snail is downregulated in gastric cancer cells overexpressing Flotillin-1." (PMID 35990908, 2022). "The protein expression of Snail is upregulated by overexpressing Flotillin-1, and overexpression of Flotillin-1 delays the degradation of Snail in gastric cancer cells." (PMID 35990908, 2022).
gastric cancer (continued). "To further study the role of Flotillin-1 in gastric cancer metastasis, we knocked down Flotillin-1 in SGC-7901 and AGS cells using shRNA." (PMID 35990908, 2022). "In this study, we determined the role of Flotillin-1 in the metastasis process of gastric cancer and molecular mechanisms of Flotillin-1 in the regulation of EMT." (PMID 35990908, 2022). "We performed Transwell and wound healing assays to detect the cell migration and invasion abilities of Flotillin-1-knockdown and control gastric cancer cells." (PMID 35990908, 2022). "Together, those results shown that Flotillin-1 can participate in the development of gastric cancer." (PMID 35990908, 2022). "Compared to normal tissues, the expression level of Flotillin-1 was significantly higher in gastric cancer samples." (PMID 35990908, 2022). "Gastric cancer patients with high Flotillin-1 expression level correlated with a worse survival overall survival, advanced TNM stage and distant metastasis." (PMID 35990908, 2022). "Taken together, those results determined that Flotillin-1 promotes the EMT process in gastric cancer cells." (PMID 35990908, 2022). "In this study, we found Flotillin-1 upregulated in gastric cancer, and the high expression of Flotillin-1 correlated with a worse prognosis." (PMID 35990908, 2022). "For the first time, the association of flotillin 1 in gastric cancer has been established in our study, suggesting that flotillin 1 is a promising candidate for future biomarker development for gastric cancer." (PMID 25948494, 2015). "To assess the clinical relevance, we examined the expression of flotillin 1 in tissue microarrays containing 85 matched normal and gastric cancer tissues by immunohistochemistry." (PMID 25948494, 2015). "The expression data from clinical samples analysis revealed that the upregulation of flotillin 1 has quite a high penetrance (>40%) in gastric cancer." (PMID 25948494, 2015). "In this research, abnormal expression of flotillin 1 has been also confirmed in clinical gastric cancers in this study." (PMID 25948494, 2015). "Additionally, FLOT1 overexpressed in gastric cancer tissue when compared with the adjacent normal mucosal, and FLOT1 expression level is positively correlated with tumor stage, invasion, metastasis and patients' poor outcome." (PMID 37928269, 2023). "C, D), which indicated that FLOT1 increased gastric cancer metastasis in vivo." (PMID 37928269, 2023). "Then how was BCAR1 phosphorylated in gastric cancer cells in which FLOT1 was upregulated?" (PMID 37928269, 2023). "Moreover, BCAR1 overexpression can partially restore FLOT1 knockdown induced gastric cancer cell proliferation, migration and invasion." (PMID 37928269, 2023). "Taken together, our study indicates that, BCAR1 mediates FLOT1 induced gastric cancer progression and metastasis through ERK signaling, which may present a novel therapeutic approach for gastric cancer treatment." (PMID 37928269, 2023). "We found that overexpression of WT-BCAR1 could partially restore FLOT1 knockdown induced inhibition of gastric cancer cell proliferation, migration and invasion." (PMID 37928269, 2023). "To investigate whether BCAR1 mediates FLOT1 induced gastric cancer cell proliferation, migration and invasion, we transfected FLOT1 OE and control plasmids into BCAR1 KD HGC-27 and the corresponding control cells." (PMID 37928269, 2023). "BCAR1 knockdown could block FLOT1 induced gastric cancer cell proliferation, migration and invasion." (PMID 37928269, 2023). "Therefore, our results demonstrate Flotillin-1 participates in the development of gastric cancer, especially in promoting metastasis." (PMID 35990908, 2022). "Increased Flotillin-1 predicts a poor prognosis of gastric cancer patients." (PMID 35990908, 2022). "Flotillin-1 may interact with a deubiquitinase to inhibit the ubiquitination of Snail in gastric cancer cells to promote EMT process." (PMID 35990908, 2022).
gastric cancer (continued). "A Flotillin-1 amplification occurs in several solid tumors including gastric cancer." (PMID 35990908, 2022). "Taken together, the results show that overexpression of Flotillin-1 promotes gastric cancer cell migration and invasion and suggested that Flotillin-1 might have a role in cancer metastasis." (PMID 35990908, 2022). "In addition, the migration and invasion ability of gastric cancer cells was upregulated by overexpressing Flotillin-1." (PMID 35990908, 2022). "Knockdown of Flotillin-1 inhibits gastric cancer cells metastasis." (PMID 35990908, 2022). "However, the detailed characteristics and mechanisms of Flotillin-1 in gastric cancer have rarely been investigated." (PMID 35990908, 2022). "Knockdown of Flotillin-1 inhibited the cell metastasis in gastric cancer." (PMID 35990908, 2022). "Our findings also supported the notion that flotillin 1 is a potential biomarker that could be exploited for molecular imaging-based detection of gastric cancer." (PMID 25948494, 2015). "In addition, Flotillin-1 inhibited the degradation of Snail in gastric cancer cells." (PMID 35990908, 2022). "Thus, the results show that knockdown of Flotillin-1 inhibits gastric cancer cell migration and invasion and suggested that Flotillin-1 might have a role in cancer metastasis." (PMID 35990908, 2022). "Therefore, Flotillin-1 may interact with a deubiquitinase to inhibit the ubiquitination of Snail in gastric cancer to promote EMT process." (PMID 35990908, 2022). "Collectively, all the results above indicated that FLOT1 and BCAR1 were overexpressed in gastric cancer tissue and was closely correlated with poor prognosis in gastric cancer patients." (PMID 37928269, 2023). "To determine the oncogenic role of FLOT1 and BCAR1 in gastric cancer patients, we analyzed the expression of FLOT1, BCAR1, p-ERK1/2 and Ki67 in 80 gastric cancer samples and the paired adjacent normal gastric mucosa using IHC staining." (PMID 37928269, 2023). "Overexpression of Flotillin-1 not only promoted the migration and invasion of SGC-7901 cells, but also increased the wound healing ability of gastric cancer cells." (PMID 35990908, 2022). "Flotillin-1 is a key regulator of EMT process and promotes gastric cancer cells metastasis through inducing EMT." (PMID 35990908, 2022). "For example, flotillin-1 (FLOT1), DYNC1, and CD59 were overexpressed in colon, breast, and gastric cancer cell lines compared to normal cell lines." (PMID 28036279, 2017). "Moreover, FLOT1 mediates the levels of heterotypic signaling molecules, including TNF-α, EGF, HGF, and IGF1, across various cancers, such as breast, prostate, and gastric cancer, and oral squamous cell carcinoma." (PMID 40335491, 2025). "Furthermore, FLOT1 and BCAR1 expression is closely related to gastric cancer patients' poor outcome." (PMID 37928269, 2023). "Therefore, our study demonstrates that Flotillin-1 can participate in EMT process and promotes gastric cancer metastasis through inducing EMT." (PMID 35990908, 2022). "Re-expression of wildtype rather than mutant BCAR1 (Y410F) could partially restore FLOT1 knockdown induced gastric cancer cell migration and invasion, while the restore could be inhibited by ERK inhibitor." (PMID 37928269, 2023). "Thus, our findings confirm that BCAR1 mediates FLOT1 induced gastric cancer progression and metastasis through ERK signaling, which may provide a novel pathway for gastric cancer treatment." (PMID 37928269, 2023). "In this study, we demonstrated that FLOT1 promotes gastric cancer cell proliferation, migration and invasion in vitro and in vivo through BCAR1/ERK signaling, and regulates BCAR1 phosphorylation and translocation, which may provide a novel therapeutic target for gastric cancer treatment." (PMID 37928269, 2023).
prostate carcinoma (7 papers, 2017 to 2025). A carcinoma that arises from epithelial cells of the prostate gland. "Based on TCGA data, FLOT1 expression is associated with FLNA expression in prostate cancer, consistent with the evidence above." (PMID 39404386, 2024). "Our findings thus provide the underlying molecular mechanisms of IGF-1-induced prostate cancer proliferation, progression, and metastasis controlled by post-translational modifications of Flot-1." (PMID 30631151, 2019). "Nuclear-targeted sumoylated Flot-1 associates with Snail to block proteasomal degradation of Snail, thereby boosting the metastatic potential of prostate cancer via Snail-mediated EMT." (PMID 30631151, 2019). "Flotillin-1 has been shown to be SUMOylated on several target lysines in cell lines and in a cellular model of prostate cancer." (PMID 34887727, 2021). "Our findings provide novel insights into the regulatory cross-talk, and spatio-temporal dynamics between sumoylation and palmitoylation of Flot-1 in prostate cancer cell proliferation, progression, and metastasis." (PMID 30631151, 2019). "To explore the regulatory role of Flot-1 sumoylation in prostate cancer, we examined mitogen-response sumoylation of Flot-1, and its relation to the metastatic potential, comparing PC3 and LNCaP cells with high and low metastatic potential, respectively." (PMID 30631151, 2019). "Nevertheless, the regulatory mechanisms by post-translational modifications, and nuclear translocation of Flot-1 in prostate cancer progression and metastasis remain to be explored." (PMID 30631151, 2019). "Sumoylation of Flot-1 by up-regulated UBC9 in human metastatic prostate cancer tissues and prostate cancer cells with high metastatic potential positively correlated with the stabilization of Snail and the induction of Snail-mediated EMT genes in the metastatic prostate cancer." (PMID 30631151, 2019). "Together, these data suggest that palmitoylation of Flot-1 regulates prostate cancer cell proliferation via IGF-1R signaling activation in the PM, while sumoylation of Flot-1 promotes EMT in metastatic prostate cancer via regulation of Snail stability in the nucleus." (PMID 30631151, 2019). "Thus our data indicate that sumoylation of the non-palmitoylable Flot-1 is likely to take place in the ER by ER-localized UBC9, and the sumoylated Flot-1 is translocated to the nucleus to stabilize Snail for the EMT of metastatic prostate cancer in mitogenic response." (PMID 30631151, 2019). "Research indicates that FLOT1 palmitoylation in the endoplasmic reticulum (ER) is necessary for IGF1R transport, which impacts prostate cancer cell proliferation." (PMID 40335491, 2025). "For instance, the SUMOylation of flotillin-1 at lysine-51 and lysine-195 in prostate cancer cells enhances the stabilization of Snail and induces the upregulation of EMT-related genes, thus enhancing the metastatic potential of prostate cancer." (PMID 34950583, 2021). "DU145 cells, another prostate cancer cells with high metastatic potential, also exhibited the elevated expression of Snail and UBC9, and the mitogen-response sumoylation of Flot-1 by SUMO-2/3." (PMID 30631151, 2019). "The present study shows that the sumoylated Flot-1 originating from the non-palmitoylable Flot-1 translocates to the nucleus in mitogenic response, and is responsible for the Snail stability to enhance metastatic potential in prostate cancer." (PMID 30631151, 2019). "IGF-1 induced PC3 cell proliferation, and the proliferation was increased by WT Flot-1 or KR mutant, but not CA mutant overexpression, suggesting that palmitoylation, but not sumoylation, of Flot-1 is responsible for IGF-1R signaling-mediated prostate cancer cell proliferation." (PMID 30631151, 2019).
cervical carcinoma (6 papers, 2013 to 2024). A carcinoma arising from either the exocervical squamous epithelium or the endocervical glandular epithelium. "Overall, this study showed that FAM201A promoted cervical cancer progression and metastasis by targeting the miR-1271-5p/FLOT1 axis-induced Wnt/β-catenin pathway." (PMID 36226250, 2022). "A previous study showed that miR‐485‐5p suppressed the invasion of cancer cells by targeting FLOT‐1 in HPV‐infected cervical carcinoma cells." (PMID 33828164, 2021). "Moreover, FAM201A drives cervical cancer progression by targeting the miR‐1271‐5p/FLOT1 axis, ultimately activating the Wnt/β‐catenin pathway." (PMID 38827027, 2024). "In that report, we also showed that IGF-1 induces depalmitoylation and repalmitoylation, a dynamic palmitoylation turnover, of the PM-targeted Flot-1, which facilitates prolonged activation of IGF-1R on the cell surface and hence promotes cervical cancer cell proliferation." (PMID 30631151, 2019). "EGFR is not upregulated e.g. in human breast epithelial MCF10A, cervix carcinoma HeLa or human keratinocyte HaCat cells upon stable flotillin-1 knockdown (our unpublished findings)." (PMID 24304721, 2013).
lung adenocarcinoma (6 papers, 2014 to 2026). A carcinoma that arises from the lung and is characterized by the presence of malignant glandular epithelial cells. "It has also been demonstrated that flotillin-1 plays an important role in cellular proliferation, and its increased expression correlates with poor outcome in patients with breast cancer and lung adenocarcinomas." (PMID 24533441, 2014). "FLOT1 affects the progression of lung adenocarcinoma by regulating the Erk/Akt signaling pathway." (PMID 33568633, 2021).
lung cancer (6 papers, 2016 to 2025). A malignant neoplasm involving the lung. "In accordance with the Minimal Information for Studies of EVs 2024 (MISEV), several known EV markers, including CD9, CD81, Flotillin-1, and TSG101, were observed in the purified serum EVs of patients with lung cancer and healthy individuals." (PMID 41007624, 2025). "Flotillin-1(FLOT1), a marker of lipid raft, is recently reported to be overexpressed and correlate with advanced tumor stage as well as poor patient survival in various types of human cancer, including breast, esophageal, liver and lung cancer." (PMID 26646322, 2016). "It was reported that FLOT1 could be a potential biomarker candidate for invasive breast, gastric, and lung cancers but no such report about FLOT1 in OC." (PMID 40066501, 2025).